PTENP1 (phosphatase and tensin homolog pseudogene 1)
Synonyms: PTEN2; psiPTEN; PTH2; PTEN-rs; PTENpg1
Gene: Transcribed processed pseudogene on chromosome 9 (33,675,437 to 33,676,651, reverse strand). Ensembl gene ENSG00000237984.
Diseases named in the same sentence as PTENP1 in open-access papers:
PTENP1 is named in the same sentence as 55 diseases in open-access papers, as found by Europe PMC text mining. Sharing a sentence is not in itself a finding about the gene and the disease. The quoted sentences say what the papers report.
breast carcinoma (29 papers, 2014 to 2026). "In breast cancer, cervical cancer, head and neck squamous cell carcinoma, hepatocellular carcinoma and oral squamous cell carcinoma, down-regulation of PTENP1 has been linked with poor survival of patients." (PMID 35655204, 2022). "Low levels of PTENP1 have been shown to be associated with increased proliferation, migration, invasion and colony formation, as well as decreased apoptosis, in breast cancer." (PMID 34527584, 2021). "Consistently, PTEN and PTENP1 downregulation was significantly associated with poor prognosis of breast cancer patients." (PMID 34065631, 2021). "There are three lncRNAs are confirmed to be associated with breast cancer in the Lnc2cancer database, which are PTENP1, SNHG16 and TUSC7, respectively." (PMID 33980147, 2021). "Finally, the sponging role of PTENP1 on miR-19b has been shown to be implicated in the suppression of proliferation and of breast cancer cells." (PMID 35655204, 2022). "Thus, we predict that disrupted YY1-EZH2 interaction, by either YPB or OPB peptide, would cause significant gene expression perturbation in breast cancer cells with PTENP1 as a primary target, leading to apoptotic cell death." (PMID 34065631, 2021). "Using ChIP-seq analysis, we demonstrated that YPB and OPB peptides could decrease H3K27 trimethylation of the PTENP1 gene, and the upregulated PTENP1 expression was a primary reason of reduced proliferation of breast cancer cells caused by the treatments of the two peptides." (PMID 34065631, 2021). "Taken together, these findings suggest that the PTENP1/miR-20a/PTEN axis contributes to the malignant behaviors of breast cancer cells, likely through modulation of the PI3K/AKT pathway by PTEN." (PMID 41362671, 2026). "Another study has found that alterations in the expression of the phosphatase and tensin homolog pseudogene 1 (PTENP1) affect breast cancer cell proliferation, invasion, tumor formation, and resistance to the chemotherapeutic drug adriamycin." (PMID 41362671, 2026). "Bioinformatic analysis and luciferase reporter assays indicate that PTENP1 is a direct target of miR-20a, uncovering an alternative mechanism through which PTENP1 affects the aggressive behavior of breast cancer cells." (PMID 41362671, 2026). "Consistent with the previous findings, increased expression of PTENP1 can inhibit breast cancer cell growth, metastasis, and tumor formation by suppressing miR-19b and promoting the expression of the PTEN tumor suppressor in breast cancer." (PMID 41362671, 2026). "PTENP1 also contributes to intra-S to G2/M phase arrest by targeting CDK2-cyclin A2 in breast cancer cells, suggesting its relevance in cell cycle regulation." (PMID 39125832, 2024). "Experimentally overexpressed PTENP1 in BC cell lines resulted in limited breast cancer cell viability and reduced proliferation, migration and invasion capabilities." (PMID 38277283, 2024). "Several studies that focused on PTENP1 published to date provide additional support for the role of PTENP1 as a tumor suppressor in breast cancer." (PMID 38277283, 2024). "PTENP1 is lost in melanoma, breast cancer, sporadic colon cancers, and in endometrioid endometrial carcinoma." (PMID 37894321, 2023). "For breast, lung, and oral squamous cell carcinomas, the normal cell-secreted exosomal PTENP1 mediates intercellular communication by promoting apoptosis in breast cancer cells as well as inhibiting invasion and migration." (PMID 36203417, 2022). "PTENP1 has also been shown to influence proliferation, invasive properties and resistance of breast cancer cells to Adriamycin." (PMID 35655204, 2022). "Recent studies have found that exosomes derived from bone marrow MSCs carry ncRNAs that can suppress cancer, including lncRNA PTENP1, which can suppress bladder cancer, and microRNA-551b-3p, which can suppress breast cancer." (PMID 36203417, 2022).
breast carcinoma (continued). "LncRNA PTENP1 is a tumor-promoting factor in breast cancer that not only affects breast cancer progression but also influences drug sensitivity." (PMID 33670518, 2021). "Although previous study demonstrated a tumor-promoting role of PTENP1 in breast cancer, another study reveals the tumor-suppressing role of this important lncRNA." (PMID 33670518, 2021). "To date, aberrant expression of PTENP1 has been found in various malignancies, including breast cancer." (PMID 34527584, 2021). "Remaining 2 cancer cell lines that had unmethylated region of the PTENP1 were obtained from pancreatic adenocarcinoma and breast cancer (COLO-357 and SKBR-3 respectively)." (PMID 33481830, 2021). "Various studies demonstrated the activity of PTENP1 in inhibiting breast cancer cell proliferation through promoting PTEN expression." (PMID 34065631, 2021). "PTENP1 functions as a ceRNA and suppress tumor progression in multi-cancers, including breast cancer, HCC, oral squamous cell carcinoma, esophageal squamous cell carcinoma, clear-cell renal cell carcinoma, gastric cancer and bladder cancer." (PMID 32185172, 2020). "In breast cancer, upregulation of PTENP1 expression can inhibit proliferation, metastasis and tumorigenicity of breast cancer cells, and enhance chemosensitivity through functioning as a sponge for miRNA-20a." (PMID 31681595, 2019). "We have observed differential co-expression patterns of PGG families in tumor vs normal tissue for PTENP1 network in multiple cancers including breast cancer." (PMID 31029062, 2019). "To the best of our knowledge, we present the first analysis of PTENP1 gene expression in human breast cancer." (PMID 28213783, 2017). "Here, we examined the prognostic and predictive value of PTEN and PTEN pseudogene (PTENP1) gene expression in patients with locally advanced breast cancer given neoadjuvant chemotherapy." (PMID 28213783, 2017). "The results confirmed that YPB and OPB peptides may decrease EZH2 recruitment to the promoters of target genes, such as PTENP1 and enhance anticancer activities reducing breast cancer cell proliferation and xenograft tumor formation." (PMID 38277283, 2024). "The PTENP1 promoter has been shown to be hypermethylated in pancreatic adenocarcinoma, breast cancer, cervical cancer, ovarian cancer, and hepatocellular carcinoma cell lines, as well as in lymphoma, colorectal cancer, clear cell renal carcinoma cells, and NSCLC tissues." (PMID 37894321, 2023). "Consequently, low PTENP1 expression promoted the malignant behavior of breast cells, while overexpression of PTENP1 suppressed breast cancer progression." (PMID 36905871, 2023). "Expression levels of PTENP1 have also been assessed in breast cancer cells." (PMID 35655204, 2022). "PTENP1 could also suppress proliferation and migratory aptitude of breast cancer cells via decreasing expressions of cell cycle regulators cyclin A2 and CDK2 and regulating activity of AKT and MAPK pathways." (PMID 35655204, 2022). "PTENP1 has been implicated in the regulation of the PI3K/Akt signaling pathway, which plays a pivotal role in tumorigenesis and tumor development, particularly in breast cancer." (PMID 34527584, 2021). "Next, we tested whether YPB- and OPB-mediated PTENP1 upregulation played a crucial role in reduced proliferation of breast cancer cells." (PMID 34065631, 2021). "PTENP1 was reported as a tumor suppressor in development and progression of breast cancer." (PMID 32185172, 2020). "We found PTENP1 to be expressed in 222 out of 318 human breast cancer samples analyzed." (PMID 28213783, 2017).
breast carcinoma (continued). "In this light, our observation of a deactivation - in breast cancer - of the sponge mechanism involving PTENP1 - together with the previously reported growth-suppressive role of PTENP1 - corroborates the importance of miRNA-mediated PTENP1 regulation in cancer." (PMID 25033876, 2014). "Moreover, PTENP1 inhibited the growth rate of ER-negative C3HBA murine breast cancer xenografts." (PMID 38277283, 2024). "In addition, PTENP1 hinders breast cancer progression through regulating PTEN/PI3K/AKT pathway." (PMID 34427967, 2021). "Interestingly, the involvement of PTENP1 in breast cancer biology may depend on the hormone receptor status." (PMID 34527584, 2021). "Overall, based on the experimental data presented above, both YPB and OPB peptides could disrupt YY1-EZH2 interaction, decrease EZH2 recruitment by YY1 to the promoters of target genes, such as PTENP1, and reduce breast cancer cell proliferation and xenograft tumor formation." (PMID 34065631, 2021). "For example, PTENP1 was found to upregulate PTEN transcript expression and inhibit cell proliferation and migration through decoying miR‐19b in breast cancer." (PMID 37929660, 2024). "In breast cancer cell lines expressing PTEN protein, PTENP1 was found to be methylated in MDA-MB-231 cells but unmethylated in MCF-7 cells." (PMID 37894321, 2023). "In breast cancer, PTEN is influenced positively by the increased expression of PTENP1 and decreasing miR-20a levels." (PMID 37894321, 2023). "LncRNA PTENP1 reduces PTEN expression via miRNA-20a sponging to upregulate PI3K/Akt signaling, resulting in breast cancer proliferation, metastasis, and adriamycin resistance." (PMID 33670518, 2021). "PTEN pseudogene-1 (PTENP1), the pseudogene of PTEN, acts through ceRNA mechanism to inhibit cancer progression in prostate cancer and breast cancer." (PMID 33995499, 2021). "It is worth noting that PTENP1 and KRASP1, the two initial examples of pseudogene ceRNAs, are present (though at low levels) in the breast cancer samples we study here." (PMID 25765044, 2015). "The data obtained in this study from the screening and validation experiments confirmed that PTENP1, GNG12-AS1, MAGI2-AS3 and MEG3 may have, or provide support for, potential tumor suppression roles in breast cancer." (PMID 38277283, 2024). "It seems that lncRNA PTENP1 functions as a double-edged sword in breast cancer, and its exact role is not certain." (PMID 33670518, 2021). "To evaluate the contribution of PTENP1 to reduced breast cancer cell viability in response to the YPB and OPB peptides, we generated two shPTENP1 constructs, which reduced PTENP1 to about 40% of its original level, and carried out the cotreatments by these shRNAs and peptides." (PMID 34065631, 2021). "Long non-coding RNA PTENP1, the pseudogene of PTEN tumor suppressor, has been reported to exert its tumor suppressive function via modulation of PTEN expression in many malignancies, including breast cancer (BC)." (PMID 31196157, 2019).
gastric cancer (25 papers, 2015 to 2025). A primary or metastatic malignant neoplasm involving the stomach. "Association between a number of tag single nucleotide polymorphisms within PTENP1, including rs7853346 C > G, rs865005 C > T, and rs10971638 G > A and susceptibility to gastric cancer has been assessed in a Chinese population." (PMID 35655204, 2022). "Association between PTENP1 polymorphisms and susceptibility to cancer has been evaluated in Chinese gastric cancer patients." (PMID 35655204, 2022). "Lei Dong etc. reported serum lncRNAs: CUDR, LSINCT-5 and PTENP1 were identified as diagnostic marker for gastric cancer." (PMID 26674525, 2015). "As a result, rs7853346 may change the folding architectures, revealing that SNPs could involve in the gastric cancer risk through modifying the specific structural motifs of PTENP1 and impacting PTENP1 stability or interaction with other molecules." (PMID 28931965, 2017). "Patients with gastric cancer (GC) are characterized by lower serum levels of PTENP1 pseudogene, which shows a diagnostic ability (AUC > 0.8) when compared with healthy controls." (PMID 27329719, 2016). "The clinical relevance of PTENP1 is underscored by its frequent downregulation in gastric cancer, squamous cell carcinoma, and other malignancies, where reduced PTENP1 expression correlates with decreased PTEN levels and worse clinical outcomes." (PMID 41473691, 2025). "PTENP1 has been observed to be downregulated in the sera of patients with gastric cancer and, with the exception of carcinomas, in osteosarcoma." (PMID 38277283, 2024). "Apart from PTENP1, some pseudogene-derived lncRNAs were also demonstrated to be downregulated in gastric cancer and play tumor suppressive roles in gastric cancer progression." (PMID 32185172, 2020). "In gastric cancer, PTENP1 overexpression led to increased PTEN mRNA and PTEN protein levels, decreased cell proliferation and induced apoptosis, and inhibited migration and invasive ability of gastric cancer cells." (PMID 32314732, 2020). "PTENP1 has been demonstrated to function as a tumor suppressor in several cancer cells, containing gastric cancer." (PMID 32185172, 2020). "Previous studies have reported that serum PTENP1 can distinguish patients with gastric cancer or clear cell renal cell carcinoma from healthy controls and PTENP1 functions as a vital tumor suppressor for HCC." (PMID 32733618, 2020). "In gastric cancer, PTENP1 was confirmed by binding miR-106b/ miR-93, in a ceRNA modulation manner, further affected PTEN level." (PMID 31196157, 2019). "Likewise, a serum three-lncRNA signature consisting of PTENP1, LSINCT-5 and CUDR (also known as UCA1) significantly outperformed CEA and CA19-9 in gastric cancer diagnostic studies." (PMID 35729321, 2022). "In gastric cancer patients, plasma levels of urothelial cancer associated 1 (UCA1/CUDR), long stress-induced non-coding transcript 5 (LSINCT-5), phosphatase and tensin homolog pseudogene 1 (PTENP1), and cytoskeleton regulator RNA (CYTOR/LINC00152) were higher than in healthy individuals." (PMID 29614786, 2018). "Long noncoding RNA (lncRNA) phosphatase and tensin homolog pseudogene 1 (PTENP1) is significantly downregulated in gastric cancer (GC), playing critical roles in GC progression." (PMID 28931965, 2017). "For example, a signature composed of three lncRNAs (PTENP1, LSINCT-5, and CUDR) significantly outperforms CEA and CA19-9 in gastric cancer diagnosis studies." (PMID 38516191, 2024). "For example, PTENP1 serves as ceRNA to control PTEN level through sponging miR-106b and miR-93 in gastric cancer." (PMID 32787827, 2020). "Three important examples are PTENP1, E2F3P1, and OCT4-pg1 in renal cell carcinoma, hepatocellular carcinoma, and gastric cancer, respectively." (PMID 31947507, 2020). "What’s more, PTENP1 functions to modulate PTEN expression by sponging miR-93 and miR-106b, plays a tumor suppressive role in gastric cancer." (PMID 32185172, 2020).
gastric cancer (continued). "Recently, lncRNA PTENP1 and PTEN expression were found to be decreased in some cancer types, including hepatocellular carcinoma (HCC), gastric cancer and head and neck squamous cell carcinoma (HNSCC)." (PMID 31196157, 2019). "However, by overexpressing PTENP1 in gastric cancer, both PTEN underexpression and cell proliferation are mitigated via the regulatory relationship between PTEN and PTENP1." (PMID 31029062, 2019). "The serum three-lncRNA signature including CUDR, LSINCT-5 and PTENP1 may be a more accurate biomarker than CEA and CA19-9 for the diagnosis of gastric cancer and facilitate the detection of gastric cancer at the early stage." (PMID 27793008, 2016).